ADH1B (alcohol dehydrogenase 1B (class I), beta polypeptide)
Diseases named in the same sentence as ADH1B in open-access papers (continued):
Sharing a sentence is not in itself a finding about the gene and the disease.
alcohol dependence (continued). "Because acetaldehyde induces unpleasant or toxic effects, people carrying alleles of ADH1B and other alcohol-metabolizing enzymes that lead to acetaldehyde accumulation may consume less alcohol to avoid acetaldehyde’s effects and may therefore be less likely to develop alcohol dependence." (PMID 17718396, 2007). "ADH1C*1 also has been related to protection against alcohol dependence, but this association has been attributed to the ADH1C gene being in close proximity to the ADH1B gene on the chromosome so that the genotypes are correlated." (PMID 17718397, 2007). "Variants of three genes encoding alcohol-metabolizing enzymes, the aldehyde dehydrogenase gene ALDH2 and the alcohol dehydrogenase genes ADH1B and ADH1C, have been associated with reduced rates of alcohol dependence." (PMID 17718397, 2007). "Compared with a Chinese man carrying two active ALDH2*1 alleles and the two copies of the normal ADH1B*1 allele, the odds ratio for risk for alcoholism for a Chinese man carrying one inactive ALDH2*2 allele and two ADH1B*1 alleles is 0.33." (PMID 17718394, 2007). "The increased enzymatic activity of ADH1B*2 and ADH1B*3 may protect against alcoholism, and consequently against FAS in the offspring." (PMID 38886650, 2024). "Therefore, a combination of a high metabolism activity (ADH1B*2 and ADH1B*3) and the inactive form ALDH2*2 will be associated with less alcohol dependence due to the “flushing” effect, an unpleasant phenomenon after alcohol consumption." (PMID 38886650, 2024). "Besides, the largest GWAS of alcohol dependence revealed that ADH1B played an important role in the etiology of alcohol dependence among Europeans and African‐Americans." (PMID 37795758, 2023). "Other variations in ADH and ALDH genes may also affect the risk of alcohol dependence and abuse, as ADH1C*1 and ADH1B*." (PMID 34680127, 2021). "Our previous multiple logistic regression analyses also suggest that ADH1B*2 and ALDH2*2 may independently influence the risk for alcoholism." (PMID 34439848, 2021). "Investigation is warranted, in a future study, of whether and how the combination of alcohol flushing status and the ALDH2 plus ADH1B genotype might affect drinking behaviors and manifestations of alcohol-related problems." (PMID 34310648, 2021). "The 10th SNP is within the region of ADH1B, which is also known to be related with alcoholism." (PMID 32093702, 2020). "It has been reported that both ADH1B and ALDH2 present strong association with alcohol dependence." (PMID 32300124, 2020). "A second ADH1B gene variant, the ADH1B*3 allele, has been related to lower rates of alcohol dependence in many but not all association studies." (PMID 27163368, 2016). "Some studies showed that ADH1C*1 and ADH1B*2 are in linkage disequilibrium, suggesting that associations of ADH1C*1 with alcohol dependence may be attributed to correlation with ADH1B*2." (PMID 27163368, 2016). "But in the European populations, the promoter derived allele does not appear together with ADH1B*47His, implying that ADH1B*47His is solely responsible for the decrease in the risk for alcoholism." (PMID 18382665, 2008). "For example, certain ADH1B and ADH1C alleles encode particularly active ADH enzymes, resulting in more rapid conversion of alcohol (i.e., ethanol) to acetaldehyde; these alleles have a protective effect on the risk of alcoholism." (PMID 17718394, 2007). "In European or African populations, the ADH1B*2 allele is not very common but also provides protection against alcoholism." (PMID 17718394, 2007). "Among the Mission Indians, those carrying an ADH1B*3 allele were about one-third less likely to have a lifetime diagnosis of alcohol dependence than were people without this allele." (PMID 17718395, 2007). "ADH1B and ALDH2 are the genes most strongly associated with risk for alcoholism." (PMID 17718394, 2007).
alcohol dependence (continued). "In that study, participants with at least one ADH1B*3 allele were significantly less likely to have a family history of alcohol dependence than those without the allele." (PMID 17718396, 2007). "Generally, individuals with the ADH1B*2 variant or the low-activity ALDH2 variant tend to consume less alcohol because of the toxic and unpleasant effects of acetaldehyde, which offers protection against alcohol dependence and alcohol-related hepatocellular carcinoma." (PMID 40943250, 2025). "Since acetaldehyde has aversive effects, variants of ADH1B and ALDH2 that increase the levels of acetaldehyde are associated with aversion to alcohol, whereas variants associated with decreased acetaldehyde are associated with increased alcohol consumption and alcohol dependence." (PMID 37792698, 2023). "However, the combination of ADH1B * 1 / * 1 and ALDH2 * 1 / * 2 also has a high risk of alcoholism." (PMID 36028843, 2022). "The risk of alcohol dependence (AD) in Japanese men and women was evaluated according to combinations of alcohol flushing and aldehyde dehydrogenase-2 (ALDH2, rs671) and alcohol dehydrogenase-1B (ADH1B, rs1229984) genotypes, all of which are known to determine AD susceptibility in Asians." (PMID 34310648, 2021). "In ALDH2*1/*1 individuals (i.e., ALDH2*1 homozygotes), one ADH1B*2 allele was associated with about one-fourth (OR = 0.26) and two ADH1B*2 alleles were associated with about one-fifth (OR = 0.20) the risk of alcohol dependence compared with individuals with no ADH1B*2 alleles." (PMID 27163368, 2016). "Similar to the results from meta- analyses showing that the ALDH2 and ADH1B genes may have an interactive effect on alcohol dependence, some self-report and alcohol-challenge data in Asians suggest that the effects of ADH1B*2 may be stronger in individuals with ALDH2*1/*2 genotype." (PMID 27163368, 2016). "ADH1B*2 also no longer showed any association with alcohol dependence in antisocial alcoholics." (PMID 27163368, 2016). "However the decrease in the risk for alcoholism has not been argued to be the selective force, and our results argue that selection is not solely related to ADH1B*47His." (PMID 18382665, 2008). "The ADH1C*1 allele also appears to have protective effects against alcoholism in Asian populations; however, this protection can be attributed to the fact that this allele usually is co-inherited with the protective ADH1B*2 allele and is not an independent effect of the ADH1C*1 allele." (PMID 17718394, 2007). "The ADH1B*3 polymorphism overall is less common but is prevalent in African Americans, in whom it has been associated with a lack of family history of alcoholism and with altered expectations of the effects of alcohol, suggesting a protective effect for this allele as well." (PMID 17718395, 2007). "Among the identified genes, the ones that stand out are ADH1B and ALDH2, which are included in the metabolism of alcohol and have the greatest impact on the manifestation of alcohol dependence." (PMID 40408386, 2025). "Previous studies have revealed protective roles of the ADH1B*2(+) and ALDH2*2(+) genotypes against the development of alcohol dependence." (PMID 35670037, 2023). "Age-adjusted odds ratios (95% confidence intervals) of alcohol dependence according to alcohol flushing status and/or the combinations of ALDH2 and ADH1B genotypes in the female subjects." (PMID 34310648, 2021). "Age-adjusted odds ratios (95% confidence intervals) of alcohol dependence according to the combinations of alcohol flushing status and ALDH2 and ADH1B genotypes in the female subjects." (PMID 34310648, 2021). "Age-adjusted odds ratios (95% confidence intervals) of alcohol dependence according to the combinations of alcohol flushing status and ALDH2 and ADH1B genotypes in the male subjects." (PMID 34310648, 2021).
alcohol dependence (continued). "Age-adjusted odds ratios (95% confidence intervals) of alcohol dependence according to alcohol flushing status and/or the combinations of ALDH2 and ADH1B genotypes in the male subjects." (PMID 34310648, 2021). "ADH1B and ALDH2 may be responsible for alcoholism protection in Asian populations, and the AGO gene cluster is related to RNA interference and silencing." (PMID 35350227, 2022). "Congruent with the general lower likelihood of predicted alcohol dependence by rs1229984 in ADH1B, there is no history of alcohol addiction in the family." (PMID 33763108, 2021). "A study comparing ALDH2 and ADH1B allele status in Taiwanese with and without ASPD and/or alcohol dependence found that ALDH2*2 showed reduced association with alcohol dependence in people with ASPD compared with people without ASPD." (PMID 27163368, 2016). "The lack of understanding of why this enzyme protected against alcoholism stems from the fact that acetaldehyde in humans carrying the ADH1B*2 was determined in venous blood; being close to zero." (PMID 23847486, 2013). "Others report that ADH1B*47His was not always related to alcoholism, especially in Taiwanese populations, in which the frequency of the ADH1B promoter derived allele is very low as we revealed in our study." (PMID 18382665, 2008). "Regardless of ADH1B genetic polymorphisms, the results also indicate that ALDH2*2 plays a major role for acetaldehyde-related physiological negative responses and prove the genetic protection against the development of alcoholism in East Asians." (PMID 34439848, 2021). "In addition, unlike the FAS population, they also have the ADH1B*3 (rs2066702) and ADH1C*1 (rs1693482) polymorphisms, which cause a faster accumulation of acetaldehyde in the blood when they drink alcohol, protecting them from possible alcoholism in adulthood." (PMID 38886650, 2024). "Never or former flushing markedly increased the ORs of alcohol dependence among carriers of any ALDH2 and ADH1B genotype combination, compared with current flushing." (PMID 34310648, 2021). "When the combination of the current flushing, ALDH2*1/*2, and ADH1B*2/*2 was used as a reference, the never or former flushing was markedly increased the ORs of alcohol dependence in the carriers of each ALDH2 and ADH1B genotype combination." (PMID 34310648, 2021).
esophageal cancer (25 papers, 2009 to 2025). A primary or metastatic malignant neoplasm involving the esophagus. "Single nucleotide polymorphisms of ADH1B are associated with the risk of alcohol-related cancers, such as esophageal cancer, head and neck squamous cell cancer, liver cancer, stomach cancer, and colorectal cancer." (PMID 39884577, 2025). "Although the impact of ADH1B on esophageal cancer risk is well documented, this is the first identification of the genetic contribution of the other four (GCKR, KLB, ALDH1A1, and ALDH2) to esophageal cancer risk." (PMID 38277453, 2024). "The two genetic variants in the Chinese alcohol metabolizing‐related genes ALDH2 (rs671) and ADH1B (rs1229984 and rs2066702) that greatly alter alcohol metabolism and had a higher risk of acetaldehyde accumulation and esophageal cancer." (PMID 36655102, 2023). "Our finding was consistent with a previous study reporting that the ADH1B rs1229984 CC genotype was associated with a 4.02‐fold increased risk of esophagus cancer relative to the heterozygous CT genotype at 1.58‐fold." (PMID 35670037, 2023). "Two meta‐analyses investigating the effect of genetic variations in ADH1B His47Arg (T/C) also showed these to be susceptible loci for esophageal cancer." (PMID 35670037, 2023). "We found that the C allele of ADH1B rs1229984 is an important risk factor for esophageal cancer, which was significantly promoted by the interaction of the ADH1B rs1229984 TC/CC genotype and ALDH2 rs671 GA/AA genotypes." (PMID 35670037, 2023). "Looking at ADH1B * 1 / * 1 alone, the risk of esophageal cancer in drinkers was 2.71–3.22 times higher; however, the combination of ADH1B * 1 / * 1 and ALDH2 * 1 / * 2 had 12.45 times higher risk." (PMID 36028843, 2022). "In conclusion, our meta-analysis suggested that ADH1B Arg47His polymorphism was significantly associated with the decreased overall cancer risk, especially for esophageal cancer and head and neck cancer amongst Asians." (PMID 30872408, 2019). "Our results suggested that ADH1B gene Arg47His variant was associated with the decreased esophageal cancer risk." (PMID 27450204, 2016). "Several studies have identified the association between ADH1B polymorphism and esophagus cancer susceptibility." (PMID 27450204, 2016). "Fifteen studies estimated the combined effect of ADH1B Arg47His polymorphism and alcohol drinking on esophageal cancer risk." (PMID 27450204, 2016). "This study is to investigate the role of alcohol dehydrogenase 1B (ADH1B) gene Arg47His polymorphism in esophageal cancer susceptibility." (PMID 27450204, 2016). "Four articles considered the combined effect of ADH1B Arg47His polymorphism and tobacco smoking on esophageal cancer susceptibility, containing 2382 patients and 4792 controls." (PMID 27450204, 2016). "Our results showed that the ADH1B Arg47His variant was correlated with the decreased occurrence of esophageal cancer under all the genetic models among total population." (PMID 27450204, 2016). "In particular, an esophageal cancer variant (rs1229984 in ADH1B) available in MEC and WHI showed an inverse association with NHL risk [OR per allele C = 0.77 (0.66–0.90), p = 4.4E-04]." (PMID 24598796, 2014). "We evaluated the association between ADH1B genotypes and susceptibility to esophageal cancer in a hospital-based case–control study." (PMID 24485404, 2014). "We investigated the associated of ADH1B SNPs with risk of esophageal cancer in a high-risk Chinese population." (PMID 24485404, 2014). "In the present study, we also found a significant gene environment interaction between ADH1B rs1229984 polymorphisms and smoking habit, suggesting susceptibility to esophageal cancer." (PMID 24485404, 2014). "In the recessive model, the ADH1B rs1229984 GG variant homozygote was associated with a 1.51-fold significantly increased risk of esophageal cancer compared with rs1229984 AA/AG genotypes (adjusted OR = 1.51, 95% CI = 1.28-1.80)." (PMID 24485404, 2014).
esophageal cancer (continued). "Two recent genome-wide association studies identified the variation of ADH1B rs1229984 as risk factors for esophageal cancer in a Japanese population." (PMID 24485404, 2014). "Multivariable logistic analysis revealed that the ADH1B rs1229984 GG genotype was associated with an increased risk of esophageal cancer, and that this effect was more evident among males, younger subjects and smokers." (PMID 24485404, 2014). "The CC genotype of ADH1B rs1229984 was significantly associated with cancer of the larynx, pharynx, and nasal cavities [odds ratio (OR) = 1.56, p = 0.0009], cancer of the pancreas (OR = 1.66, p = 0.018), and cancer of the esophagus (OR = 4.10, p < 0.001)." (PMID 35670037, 2023). "The CC genotype of ADH1B rs1229984 was significantly associated with cancer of larynx, pharynx, and nasal cavities (OR = 1.56, p = 0.001), cancer of the pancreas (OR = 1.66, p = 0.018), and cancer of the esophagus (OR = 4.10, p < 0.001)." (PMID 35670037, 2023). "Furthermore, Arg/Arg genotype of ADH1B Arg47His variant combined with drinking, smoking and males appeared to show a high risk in patients with esophageal cancer." (PMID 27450204, 2016). "In conclusion, our results suggested that ADH1B Arg47His polymorphism might be a protective factor on esophageal cancer susceptibility in Asians." (PMID 27450204, 2016). "Furthermore, we sought to investigate the associations between measures of ADH1B and risk of progression to esophageal cancer in gene, protein and cellular level." (PMID 24485404, 2014). "In conclusion, the present study provided marked evidence that functional polymorphism of ADH1B rs1229984 may contribute to the risk of esophageal cancer." (PMID 24485404, 2014). "The cancers associated with ADH1B rs1229984 were in the head and neck region, including cancer of the larynx, pharynx, and nasal cavities (OR = 1.68, p = 2.82 × 10−4), cancer of the hypopharynx, (OR = 3.43, p = 2.06 × 10−5) and cancer of the esophagus (OR = 3.80, p = 8.69 × 10−9)." (PMID 35670037, 2023). "Furthermore, we found that the combined effect of Arg/Arg genotype in ADH1B Arg47His variant and alcohol drinking, tobacco smoking, and male patients revealed a higher risk on esophageal cancer risk when compared with the His carrier of His/His and Arg/His genotypes, respectively." (PMID 27450204, 2016). "Of these, four (GCKR, ADH1B, ALDH1A1, and ALDH2) were found to potentially interact with rs671 on the risk of esophageal cancer." (PMID 38277453, 2024). "Of the discovered loci, four (GCKR, ADH1B, ALDH1A1, and ALDH2) were suggested to interact with rs671 in the risk of esophageal cancer, a representative alcohol-related disease." (PMID 38277453, 2024). "The ratios of esophageal cancer and alcohol dependence syndrome were 0.97% (p < 0.001) and 1.10% (p < 0.001), respectively, in the ADH1B rs1229984 CC genotype." (PMID 35670037, 2023). "A recent genome-wide association study identified the variation of ADH1B rs1229984 and ALDH2 rs671 polymorphisms as risk factors for esophageal cancer." (PMID 24485404, 2014). "Here, we provided evidence that ADH1B rs1229984 GG is one of the risks to initiate the Human esophageal cancer." (PMID 24485404, 2014). "Another genome-wide association study reported that variations of ADH1B rs1229984 and ALDH2 rs671 coupled with alcohol drinking and smoking synergistically enhanced the risk of esophageal cancer." (PMID 24485404, 2014). "Ectopic expression of ADH1B was able to significantly inhibit esophageal cancer in vitro and in vivo by increasing the consuming of alcohol." (PMID 24485404, 2014). "The interaction analysis further highlighted the potential combined effect of GCKR, ADH1B, ALDH1A1, and ALDH2 with rs671 GA toward increased (GCKR, ADH1B, and ALDH1A1) or decreased (ALDH2) risk of esophageal cancer and thereby carries important implications for personalized prevention." (PMID 38277453, 2024).